IL1B (interleukin 1 beta)
Diseases named in the same sentence as IL1B in open-access papers (continued):
Sharing a sentence is not in itself a finding about the gene and the disease.
cancer (continued). "However, the impact of BRAF(V600E) on IL-1β production and cancer evolution remains to be studied." (PMID 32635472, 2020). "Therefore, TLR-4-TRIF-NF-κB signalling might be a conserved mechanism mediating cancer cell debris-induced IL-1β production in M2 polarised macrophages." (PMID 31588122, 2019). "In addition, ISO-mediated specific inhibition of the secreted level of IL-1β suggested its anti-inflammatory effects, which could be of interest for further investigation about the anti-cancer and anti-inflammatory effects of ISO." (PMID 31817453, 2019). "However, aberrantly expressed IL-1β and IL-18 contribute to cancer pathology." (PMID 31492049, 2019). "Thus, IL-1β-induced chemoresistance in cancer cells might be attributed to its regulation of the EMT program." (PMID 31492049, 2019). "Therefore, inhibition of NLRP3 inflammasome activity and/or IL-1β secretion might be an approach to correct 5-FU ambivalent action in cancer patients." (PMID 31217433, 2019). "With regards to these results of the pro-inflammatory cytokine (IL-1β) protein expression, which has a role in cellular division, the antiproliferative effect of eugenol was, in part, attributed to its anti-inflammatory activity with downregulation of this cancer-related protein." (PMID 31684176, 2019). "In turn, caspase-1 enhances the proteolytic cleavage and the secretion of the inflammatory cytokines interleukin (IL)-1β and IL-18, leading to infiltration of more immune cells and resulting in the generation and maintenance of an inflammatory microenvironment surrounding cancer cells." (PMID 30619282, 2018). "Thus, the ligand-activated GPER triggers the Epidermal Growth Factor Receptor (EGFR)/extracellular signal–regulated kinases(ERK)/PKC signaling transduction pathway generating a feed forward loop that couples IL-1β induction by CAF to IL-1R1 expression by cancer cells." (PMID 30042333, 2018). "IL-1β is a pleiotropic cytokine and its role in cancer might be context dependent even if this statement is still under discussion since opposite outcomes have been reported ranging from cancer protection to cancer progression." (PMID 30154786, 2018). "Cancer-induced pain results from a mixture of mechanisms, including inflammatory, neuropathic, and/or ischemic components, of which, the synthesis and release of proinflammatory cytokines such as IL-1β and IL-6 may play a pivotal role." (PMID 28286408, 2017). "Moreover, multiple studies demonstrated that IL1B is related to many human cancers." (PMID 28225867, 2017). "Thus, the possibility remains is that, in addition to NAI-containing drugs directly killing cancer cells, these compounds may also cause ATP release, which then act in concert to promote P2X7-induced IL-1β release and drive antitumor immunity." (PMID 27524862, 2016). "IL-1β-induced COX-2 would mediate the evolution from inflammation to cancer through HIF-1, and such a process could be inhibited or suppressed by nonsteroidal anti-inflammatory drugs (NSAIDs), such as Aspirin and Celecoxib, leading to apoptosis of cancer cells." (PMID 27811377, 2016). "In addition, the IR induced IL-1β expression can also favour cancer cell invasion." (PMID 25705130, 2015). "In addition, IR-induced IL-1β expression can also favor cancer cell invasion." (PMID 26569225, 2015). "However, DJ-1 also plays a role in regulating IL-1β expression, and whether inflammatory microenvironment built by dysregulated DJ-1 affects cancer progression is still unclear." (PMID 25706411, 2015). "However, IL-1β and IL-23 are likely produced by other cells and may further support development of Th17 as seen in other studies of both H. pylori infection and cancer." (PMID 23365642, 2013). "Since inflammasome-mediated release of IL-1β can drive chronic inflammation with protumour activity (Apte & Voronov, 2008), this might explain why in EBV-associated cancers, the inflammasome genes are induced and activated by viral factors such as LMP1 and EBERs." (PMID 23065753, 2012).
cancer (continued). "However, due to the aggressiveness of OC and IL-1β's promotion of cancer progression, it may prove more beneficial to evaluate IL-1β as a treatment target rather than as a therapeutic agent." (PMID 21765834, 2011). "Moreover, we observed that the CCK1 receptor antagonist devazepide similarly suppressed up-regulation of ephrin B1 gene expression and IL-1β production, and that the intraperitoneal injection of sulfated CCK-8 induced the production of IL-1β in the cancer-inoculated region." (PMID 20979661, 2010). "Although the catabolism is mainly mediated by the effects of certain cytokines, such as tumor necrosis factor-α (TNF-α), interleukin-1β (IL-1β), and interleukin-6 (IL-6), the mechanisms associated with cancer related anorexia are still not elucidated completely." (PMID 20920199, 2010). "In addition, IL-1β production increased in the cancer-inoculated hind paw of mice, but could be suppressed by treatment with Z-360." (PMID 20979661, 2010). "However, the administration of Z-360 (100 mg/kg) once a day from day 7 to 14 after transplantation significantly reduced the levels of IL-1β protein in the cancer-inoculated region by 54.3% compared to the vehicle-treated group in cancer-induced pain mice (p <0.05)." (PMID 20979661, 2010). "Autophagy inhibits the “chronic inflammation–fibrosis–cancer” axis by degrading NLRP3 inflammasomes and damaged lysosomes, blocking IL-1β release." (PMID 40868135, 2025). "For instance, the production of proinflammatory cytokines such as IL-6, IL-1β, and TNF-α is downregulated by the omega-3 PUFA eicosapentaenoic acid (EPA) in healthy people and cancer patients." (PMID 40430444, 2025). "In the present study, we found that TNF, IFN, IRF1 and IRF5, IL-6, IL-1β, and CCL3 were upregulated in EBV-positive SCC25 cancer cells compared to EBV-negative SCC25 cancer cells." (PMID 39941858, 2025). "First, we compared the expression of NLRP3 (and IL‐1β and CASP‐1) in our PTCC data set with other cancer types to demonstrate that blood cancers generally express more NLRP3 (and IL‐1β and CASP‐1)." (PMID 40104043, 2025). "In fact, an increase in the tendency of cancer recurrence and metastasis was observed with increased mRNA expression levels of NLRP3, ASC, IL-1β, and caspase-1." (PMID 41440367, 2025). "This blockade is one of the major mechanisms that promote cancer progression, and it occurs under cancer conditions and is influenced by tumor-derived factors such as VEGF, IL-6, and IL-1β." (PMID 40491907, 2025). "First, it induces the production of proinflammatory cytokines such as TNF-α, IL-6, and IL-1β, as well as chemokines such as CXCL1 and CCL2, which recruit immune cells, stimulate angiogenesis, and enhance cancer cell proliferation." (PMID 40562870, 2025). "We found that the expression of CD3, CD4, CD8, CD20, IL-1β, PD-L1 and TCF-1 in the cancer nest increased after H101 injection during the first recurrence." (PMID 40661951, 2025). "In a related study, macrophages co-cultured with NRF2 active cancers were driven to an immunosuppressive M2 phenotype characterized by increased CD163 and Arg1 as well as diminished IL-6 and IL-1b." (PMID 40946102, 2025). "For example, NQO1 also inhibits cytotoxic cytokines including IL-6, IL-1B, and TNFα through TLR suppression in macrophages and microglia, a finding with clinical significance in both cancers and neurodegenerative disorders." (PMID 40946102, 2025).
cancer (continued). "Using both in vivo mouse models and in vitro cell studies, HDAC6 and IL-1β progressively increased as OSCC advanced, a pattern also reflected in human cancer datasets (TCGA-HNSCC)." (PMID 41440367, 2025). "The current view is that, on the one hand, activated immune cells secrete large amounts of inflammatory and other mediators in cancer (e.g., NF-κB, TNF-α, IL-1β, IL-6, etc.), affecting the function of distant organs, such as the heart." (PMID 40182041, 2025). "In cancer cells, these exosomes have been found enriched with certain biomolecules such as NF-κB, STAT3, and pro-inflammatory cytokines (e.g., TNF-α, IL-1β, and IL-6); this means cancer cell-derived exosomes recruit immune cells to target sites." (PMID 40443670, 2025). "In summary, SsnB exerts its anti-cancer effects by downregulating MyD88, p-ERK, and p-NFκB signaling, along with suppressing the pro-inflammatory cytokines TNF-α, IL-1β, and IL-6." (PMID 40143078, 2025). "Analysis of cytokine concentrations revealed significantly elevated levels of pro‐inflammatory cytokines, including TNF‐α, IL‐6, IL‐1β, IL‐8, and VEGF, in cancer tissues compared to adjacent tissues (Fold Change: 2.5–4.0, p < 0.05)." (PMID 40596746, 2025). "Emodin alleviates cancer pain by inhibiting P2X7R activation, reducing ATP-induced intracellular Ca2+ concentrations, decreasing IL-1β release, and lowering ROS production." (PMID 40717979, 2025). "In patients with advanced cancer, elevated CRP levels are commonly experienced in conjunction with elevated levels of IL-1β and TNF." (PMID 40420174, 2025). "In cancer cells, both SA and Dox increased pro-inflammatory cytokines (TNF-α, IL-6, IL-1β) and NO, likely contributing to an acute inflammatory response that facilitates immunogenic cell death." (PMID 41304843, 2025). "Both T2DM and cancer are characterised by elevated secretion of proinflammatory cytokines (e.g., IL-6, TNF-α, IL-1β), which can cross the blood–brain barrier and activate microglia, thereby contributing to depressive and anxiety symptoms." (PMID 41149069, 2025). "Previous studies have reported that S100A8/A9 increases the expression levels of IL-1β and CCL2 through p38 MAPK/JNK/AP-1 signaling in cancer cells 17-21." (PMID 40860162, 2025). "This heparanase expression is upregulated in astrocytes by nerve growth factor (NGF) in response to factors secreted by cancer cells, including TGF-β1, IL-1β, and bFGF." (PMID 41268299, 2025). "Subsequently, the release of IL-1β by intermediate monocytes further boosts the proliferation, migration, adhesion, and EMT of cancer cells, while concurrently reducing the apoptosis rate of cancer cells." (PMID 39958348, 2025). "In this study, we assessed the function of IL-1β in EOC cells, providing new insights into the relationship between inflammation and cancer progression." (PMID 40244135, 2025). "Suppression of IL-1β-NFκB/CREB-Wnt pathway is known to prevent both BRCA metastasis to bone in vivo, and colony formation of cancer stem cells in the bone microenvironment in vitro." (PMID 40583063, 2025). "After the second recurrence, the expression of CD3, CD4, CD8, CD20 and IL-1β increased and the expression of PD-L1 and TCF-1 decreased in the cancer nest after H101 injection." (PMID 40661951, 2025). "Active NLRP3 inflammasome signaling and IL-1β secretion have been observed in GBM, and NLRP3-driven myeloid-derived suppressor cell (MDSC) recruitment can mediate cancer immune evasion." (PMID 40377974, 2025).
cancer (continued). "Studies evaluating the expression of classic pro-inflammatory cytokines (TNF-α, IL-1β, IL-6, IL-17, IL-18, IL-33) in the spinal cord, PAG, and DRG revealed upregulation following inoculation of cancer cells to establish the BCP models." (PMID 38940936, 2024). "The interaction of IL-1β with its IL-1 Type 1 receptor (IL-1R1) activates β-catenin-dependent signaling, upregulating TWIST1 and SNAIL1 and triggering the EMT program in cancer cells." (PMID 39201656, 2024). "The different fractions reduced cancer cell clonogenicity and inhibited COX2 expression and activity induced by IL1β." (PMID 39125413, 2024). "IL-1β has been shown to stimulate the production of MMP-9 and the proto-oncogene tyrosine-protein kinase Src, which heavily encourages cancer metastasis and proliferation." (PMID 39451257, 2024). "The interaction between NLRP3 inflammasomes, inflammatory cytokines like IL-18 and IL-1b, and TNBC has been found to promote cancer development with the potential for novel anti-inflammasome treatments in this type of cancer." (PMID 39409110, 2024). "BC cell derived GLUT3 triggers lactate-mediated CXCL8 secretion by cancer cells leading to TAM M1 polarization and expression of IL-1β, TNF-α and IL-6." (PMID 39044824, 2024). "IL-1β and TNF-α also activate the MAPK pathway, increasing gene expression in those that promote cancer cell growth and inflammation." (PMID 39728433, 2024). "This activation occurs through the secretion of IL-1β, which activates the NLRP3 inflammasome signaling pathway, promoting the inflammatory microenvironment and cancer progression." (PMID 38655063, 2024). "Cancer cells secrete growth factors and cytokines (including IL-6, IL-1β, TGF-β1, TGF-β2, FGF-2, and PDGF), which help in the remodeling of the ECM and the development of the TME in cancer cells." (PMID 39518022, 2024). "Considering our observations and those of others, the activation of the MEK/ERK pathway induced by IL-1β is thought to be triggered through the IKKβ/Tpl2 cascade and be involved in EMT-related disorders such as organ fibrosis and cancer metastasis." (PMID 39118068, 2024). "It inhibits inflammatory cytokines such as TNF-α, IL-6, and IL-1β, improves cognitive functions by regulating the NGF-BDNF-CREB signaling pathway, and shows antiproliferative effects on cancer cell lines like AGS, HT-1080, and HT-29." (PMID 39124930, 2024). "The research highlights that IL-1B enhances epithelial-to-mesenchymal transition (EMT), invasion, and migration of cancer cells, and its inhibition through IL-1 β antibodies or IL-1R antagonists like Canakinumab and Anakinra reduces metastasis." (PMID 39125732, 2024). "Elevated levels of IL-1β, IL-6, and TNF-α have been demonstrated to facilitate the development of cancer." (PMID 39594117, 2024). "Although associations have been identified between IL-4, IL-6, IL-8, IL-10, IL-1β, TNF-α, COMT, CLOCK, PER, and 5-HTTLPR-related genes and cancer-related fatigue, the relationship between IL-6 and cancer-related fatigue remains controversial." (PMID 39372868, 2024). "We found that IFNA1 and IFNL1 gene transcripts resulted negligibly expressed across the pan-cancer dataset when compared to other immunosuppressive and pro-inflammatory cytokines such as TGFB1/2, PTGES2, IL1A, IL1B, IL6 and CSF1." (PMID 38239354, 2023). "IL-1β recognition trough IL1R leads to different associated kinases family (IRAK) assembly around Myd88, forming other types of macromolecular complexes (myddosomes) that may play an important role in myeloid malignancies and in the adaptative resistance to various forms of cancer therapy." (PMID 37819510, 2023). "When pyroptosis is activated, inflammatory mediators, such as IL‐1β, IL‐18, and HMGB1, are produced, all of which can have a positive impact on the progression of the cancer." (PMID 37752941, 2023).
cancer (continued). "CRP is subject to regulation by key molecular triggers of cachexia, such as IL-6, IL-1β, and TNF-α, which not only promote cancer cell growth and safeguard cancer cells against apoptosis but also stimulate angiogenesis and metastasis." (PMID 37755304, 2023). "Studies have shown that IL-1β, TNF-α, and IL-6 are the most substantially changed cytokines in cancer, and their levels can even be related to cancer stage." (PMID 36627634, 2023). "The combination of HFD plus cancer resulted in increased expression of some cytokines in the OFB (e.g., Ccl2, Ccl4, Cxcr2, Il1b) and decreased expression of others (e.g., Ccr5, Cx3cl1, eNos, Tnfa) as compared to the HFD group alone." (PMID 38264656, 2023). "Human pan-cancer and experimental NF-κB reporter, transcriptome, and proteome screens reveal that KRAS-mutant tumors trigger macrophage IKKβ activation and IL-1β release via secretory versican." (PMID 36980752, 2023). "IL1β and vascular endothelial growth factors (VEG-F) are drivers in the establishment and maintenance of cancer-related angiogenesis." (PMID 37065483, 2023). "We found that MDSC secreted cytokines IL-6, IL-10, IL-1β are the dominant factors elevating MDR expression in cancer cells, neutralization of MDSC secreted IL-6, IL-10, IL-1β reversed the MDR trait." (PMID 38304256, 2023). "Via the regulation of the interleukin-1 beta/factor nuclear kappa B (IL-1β/NF-κB) pathway, TRPML2 activation promotes cancer cell proliferation, migration, and invasion." (PMID 37892239, 2023). "Few articles investigated the predictive value of inflammatory biomarkers [interleukin (IL)-1β, IL-6, IL-10, TNF-α, and MMP-2 and -9] in the peritoneal fluid of cancer patients who underwent surgery and experienced AL in different locations." (PMID 37601530, 2023). "P2RX7 activation in macrophages and DCs releases NLRP3 to increase IL-1β and IL-18 production and NLRP3 has pro- and anti-tumorigenic roles in cancers based on cytokine quantity." (PMID 36741002, 2023). "Notably, multiple cancer therapeutic agents such as chemotherapeutic drugs, MAPK inhibitors, and BRAF V600E inhibitor (BRAFi) have been reported to either increase the expression of IL-1β or activate inflammasomes in myeloid cells causing unwanted side effects." (PMID 36161514, 2023). "When the inflammasomes are abnormally activated, a variety of inflammatory cytokines and chemokines, including TNF-α, IL-1β, IL-6, IL-18, CCL2/MCP-1, are excessively secreted, which affect the development of cancer." (PMID 37020871, 2023). "SOR reduced the level of SOX-2 that maintenance of cancer stemness and tumorigenicity, and TNF-α and IL-1β levels." (PMID 37259369, 2023). "According to reviews, increased neutrophil and monocyte counts, along with elevated levels of various inflammatory markers such as IL-6, IL-1β, and CRP, have been found to be correlated with fatigue in cancer survivors." (PMID 37507961, 2023). "In the early stage of CRLM, the adherence of disseminated cancer cells to KCs prompts KCs to capture and phagocytose the cancer cells and release TNF-α, interleukin-1α (IL-1α) and IL-1β, thus reducing the metastasis of colon cancer cells to the liver." (PMID 37480104, 2023). "This analysis suggested strong involvement of IL1B, TGFB1, and TNF in several cancer hallmarks identified in both bulk and single-cell data of MES." (PMID 37370765, 2023). "Meanwhile, the activation of NF-κb by proinflammatory stimuli such as IL-1β was reported to inhibit TGF-β-induced gene expression by increasing the inhibitory Smad7 in hematopoietic progenitors and cancer cell lines." (PMID 37215126, 2023). "The release of IL-1β, IL-8, TNF-α, TGF-β, MMP-2, and MMP-9 by macrophages is involved in epithelial-mesenchymal transition (EMT), which promotes cancer cell invasion and metastasis." (PMID 38137361, 2023).